MIR1183 (microRNA 1183)
Synonyms: hsa-mir-1183; MIRN1183
Gene: MicroRNA gene on chromosome 7 (21,471,058 to 21,471,146, forward strand). Ensembl gene ENSG00000221783.
Gene Ontology:
Biological process: miRNA-mediated post-transcriptional gene silencing
Cellular component: RISC complex